CCNE1 (cyclin E1)
Diseases named in the same sentence as CCNE1 in open-access papers (continued):
Sharing a sentence is not in itself a finding about the gene and the disease.
cancer (347 papers, 2007 to 2026). A tumor composed of atypical neoplastic, often pleomorphic cells that invade other tissues. "Potential association in different types of cancer was analyzed between CCNE1 changes and prognosis by crude analysis of the change pattern." (PMID 39591374, 2024). "High CCNE1 expression was associated with a poor overall survival prognosis in several cancers, including ACC, BRCA, KIRC, KIRP, LGG, LIHC, LUAD and MESO." (PMID 39591374, 2024). "As demonstrated in our study, high CCNE1 expression is associated with poor overall survival in several cancers, including ACC, BRCA, KIRC, KIRP, LGG, LIHC, LUAD, and MESO." (PMID 39591374, 2024). "High CCNE1 gene expression was associated with poor prognosis of OS in cancers, including ACC, BRCA, KIRC, KIRP, LGG, LIHC, LUAD, MESO." (PMID 39591374, 2024). "In this study, we performed a pan-cancer analysis for the association of CCNE1 expression with clinicopathological features of cancer." (PMID 39591374, 2024). "CCNE1 plays a critical role in cell cycle regulation, and its mutations and overexpression are closely associated with the development of various cancers." (PMID 39591374, 2024). "In different tumors, high expression of CCNE1 is associated with cancer-associated fibroblasts, especially in BRCA, COAD, LUSC, STAD, THYM." (PMID 39591374, 2024). "CCNE1 expression positively correlated with the cancer-associated immune infiltration level in BRCA, COAD, LUSC, STAD and THYM." (PMID 39591374, 2024). "The transition from G1 to S phase is driven by CDK2 in complex with its canonical partner cyclin E1 (CCNE1), which is often amplified in various cancers and is associated with worse survival outcomes in patients with breast, ovarian, and other malignancies." (PMID 38531837, 2024). "Increased expression of cyclin E1 caused by amplification of the CCNE1 gene is a common cause of replication stress in various cancers." (PMID 37067201, 2024). "A detailed analysis of different mutation types can enhance our understanding of the role of CCNE1 in cancer development and progression, providing a theoretical basis for precision medicine." (PMID 39591374, 2024). "Genetic alterations of CCNE1, including duplications and deep mutations, have been observed in various cancers." (PMID 36964635, 2023). "CCNE1 is a gene on 19q12 that is amplified in a variety of malignant tumors, associated with genomic instability and resistance to cytotoxic therapy." (PMID 36393842, 2022). "The subgroup of patients displaying high CCNE1 expression after primary cancer treatment was strongly (p = 0.000021) associated with reduced disease-free survival (DFS), pointing to enhanced risk for postcurative mortality in these patients." (PMID 34830835, 2021). "In the present study, CCNE1 is significantly overexpressed in luminal B, Her2 positive, and basal-like subtypes compared with normal samples, which suggests that the expression of CCNE1 is associated with the relatively aggressive degrees of cancer." (PMID 33313822, 2021). "Given CCNE1 amplification and BRCA1/2 mutations are mutually exclusive, there is thought that CCNE1 amplified cancers are reliant on a proficient homologous recombination pathway." (PMID 34485660, 2021). "lncRNA-microRNA-associated ceRNA has been confirmed as an important mode in progress of TNBC, and CCNE1-associated ceRNA regulation appeared in several cancers." (PMID 33791304, 2021).
cancer (continued). "Cyclin E has been implicated in various carcinomas; specifically, CCNE1 (Cyclin E1) is upregulated by HOXC13 to promote proliferation and cell cycle progression." (PMID 34692847, 2021). "Exploration of the effect of cyclin E1 amplification on the cellular machinery that causes dysregulated proliferation in cancer cells has allowed investigators to explore promising targeted therapies that provide the basis for emerging clinical trials." (PMID 32380689, 2020). "We also found copy number loss of cancer genes such as CCNE1, MAF, MAFB, MYC, ZNF479, and MGMT and copy number gain of FOXA2, CDH10, and GPC5 in at least two WDPM cases." (PMID 32545767, 2020). "Next, we tried to investigate and explain the cancer-related regulation mechanisms underlying path associations between the DNA methylation sites and CCNE1 in 2 of 10 path associations." (PMID 30944378, 2019). "Cyclin E1‐driven OvCa is characterized with activated polyamine synthesis, which is associated with decreased cancer immunity." (PMID 31657115, 2019). "Previous studies suggested that the expression of cyclin E1 is negatively associated with anti-cancer drug sensitivity." (PMID 31349793, 2019). "Amplification of CCNE1 gene encoding cyclin E1 is uncommon in HR+/HER2+ cancer subtype, although overexpression of cyclin E1 is a more common event." (PMID 30018827, 2018). "V9P represents a model for overexpression of cyclin E1, commonly observed in many cancers and which has been linked to chromosome instability." (PMID 28683746, 2017). "Other oncogenes or cancer-associated genes such as CCNE1 (19q12; O15), CD44 (11p13; Y21), CDK6 (7q21.2; Y11), GATA4 (8p23.1-p22; O19), and GATA6 (18q11.2; O17) were also located in regions with high copy number gains." (PMID 29190909, 2017). "Based on the study of cancer cell lines, loss of pRb function by gene deletion or mutation, amplification of CCNE1, and high p16 expression were often associated with resistance to the drug." (PMID 28566333, 2017). "In contrast, the genes encoding cyclin-A1, -B1, -E1 and -E2, i.e. Ccna1, Ccnb1, Ccne1 and Ccne2, were up-regulated in malignant tumors." (PMID 25900242, 2015). "Expression levels of POP4, PLEKHF1 and CCNE1 were significantly higher in cancer cells harbouring amplification of the genes encoding these proteins than in cancer cells devoid of amplification of these loci (Mann-Whitney U test P < 0.05)." (PMID 22433433, 2012). "Cyclin D1 and cyclin E1 are regulators of G1–S-phase cell cycle progression, are often constitutively expressed, and are associated with pathogenesis and tumorigenesis in most human cancers." (PMID 39940838, 2025). "In addition, genes that promote cell cycle progression such as CCNE1 and CCNB1, which encode cyclin E1 and cyclin B1, respectively, are also crucial players in cancer cell proliferation." (PMID 38538106, 2024). "Additionally, CCNE1 expression was correlated with the cancer-associated immune infiltration level in BRCA, COAD, LUSC, STAD and THYM." (PMID 39591374, 2024). "Also, the amplification or overexpression of cyclin genes, such as CCND1 and CCNE1, is associated with platinum resistance in various cancers." (PMID 37845393, 2023). "However, decrease of CCNE1 from primary colorectal carcinomas to liver metastases is seen, and reduction of cyclin E in primary carcinomas is associated with poor prognosis and metastasis to the peritoneum." (PMID 17201907, 2007). "Given that this subset of cancers are typically resistant to standard-of-care platinum chemotherapy and associated with poor overall survival, we sought to address this clinical unmet need by identifying a treatment strategy that targets critical survival pathways for CCNE1-driven cancers." (PMID 38410486, 2024).
cancer (continued). "CCNE1 mutations may lead to cell cycle dysregulation, promoting cancer cell proliferation." (PMID 39591374, 2024). "However, we investigated whether we would be able to target other concurrent genetic mutations or develop novel strategies to treat CCNE1 amplified cancer cells via synthetic lethal interaction other therapeutics, such as Wee1 kinase or CDK2 kinase inhibition." (PMID 35610322, 2022). "Although we could not identify a specific transcription factor that may be directly responsible for the downregulation of TTLL11 in cancer we found that there is a causal link between the increased expression of two oncogenes, CCNE1 and cdc25a, and the downregulation of TTLL11." (PMID 36414642, 2022). "Furthermore, other co-existing mutational events elsewhere in the cancer genome may cooperate or enhance the oncogenic effect of CCNE1 over-expression." (PMID 21103391, 2010). "Pan-cancer analyses have shown that CCNE1 is frequently overexpressed across various malignancies and is associated with poor prognosis and proliferation-related pathways, including cell cycle progression and DNA replication." (PMID 41331376, 2025). "HBV integrations have also been found to alter other cancer‐associated genes, including lysine methyltransferase 2B (KMT2B) and Cyclin E1 (CCNE1)." (PMID 39720865, 2025). "DepMap dataset revealed that there is a relatively small subset of cancer cell lines that are vulnerable to loss of CDK2 and its catalytic partner cyclin E1." (PMID 39924553, 2025). "Another cyclin gene, CCNE1 also showed a trend for higher amplification frequency in ELF3/HNF4A up-regulated cancers (Student’s t-test p = 0.06)." (PMID 41425714, 2025). "LMW-cyclin E1 can maintain the viability of cancer cells by facilitating replication stress tolerance and regulating lipid metabolism." (PMID 40959067, 2025). "Among them, 982 epithelial cells were primarily categorized into three subgroups as follows: CCNE1(+), cancer, and ciliated cells." (PMID 41024301, 2025). "Cyclin E1 (CCNE1) is an oncogenic driver gene that promotes the progression of various cancer types (e.g., lung, ovarian, endometrial)." (PMID 38994350, 2024). "Due to the role of CCNE1 in cell cycle progression, boosting the CCNE1 expression in cancer cells is predictable." (PMID 39116089, 2024). "In this study, a series of pan-cancer analyses were performed to determine the relevance of CCNE1 in pan-cancer and its potential predictive value." (PMID 39591374, 2024). "This study’s innovative approach of integrating multiple datasets provides new insights into the potential clinical applications of CCNE1 as a prognostic biomarker and its role in immune modulation across different cancers." (PMID 39591374, 2024). "The CDK2 inhibitor INX-315 induces cell cycle arrest and therapy-induced senescence, thereby controlling the growth of CCNE1-amplified cancers and CDK4/6 inhibitor-resistant breast cancers, which together supports future clinical development." (PMID 38047585, 2024). "GEPIA and Kaplan-Meier plotter databases were utilized to observe the prognostic significance of CCNE1 in cancer." (PMID 39591374, 2024). "However, in our study, there was no obvious association between CCNE1 expression and MSCs, monocytes, or bone marrow-derived suppressor cells, but the link between CCNE1 and TME through cancer-associated fibroblasts may explain the prognostic impact of CCNE1 in different cancers." (PMID 39591374, 2024). "Pharmacological inhibitors of PKMYT1 have been designed and subsequently validated in CCNE1-amplified cancer models." (PMID 38570712, 2024). "Overexpression of cyclin E1 increases the speed at which cancer cells transition from G1 to the S phase." (PMID 38894867, 2024).
cancer (continued). "The aim of this study was to develop a novel CDK2 inhibitor to provide a new therapeutic option for cancer patients with CCNE1 overexpression and resistance to CDK4/6 inhibitors." (PMID 38338471, 2024). "We first set out to determine the impact of INX-315 treatment in preclinical models of CCNE1-amplified cancers." (PMID 38047585, 2024). "Here, we describe the creation of a novel, potent, and selective inhibitor of CDK2 and characterize its activity in models of CCNE1-amplified cancer and CDK4/6i–resistant luminal breast cancer." (PMID 38047585, 2024). "Recognizing the significance of sex differences in the immune response to cancer, we initially conducted pilot experiments with male mice bearing Ccne1+ and Vgll3+ tumors, yielding comparable results in terms of immune composition and immune exclusion." (PMID 38509063, 2024). "Clinically, high CCNE1 expression has been correlated with several critical aspects of cancer behavior and patient outcomes." (PMID 39591374, 2024). "By comparing the expression of CCNE1, we investigated expression of CCNE1 among cancer types in TCGA by TIMER2." (PMID 39591374, 2024). "In subsequent studies, various cancer types have been confirmed to be closely related to CCNE1 over-expression, and the possible mechanism of action has also been analyzed." (PMID 39591374, 2024). "This study provides evidence of a significant reduction of CCNE1 expression in both cancer cell lines." (PMID 39116089, 2024). "We next tested the in vivo efficacy of INX-315 using several mouse models of CCNE1-amplified cancer." (PMID 38047585, 2024). "Binding of eIF4G to CCND1 mRNA was reduced by INK128 treatment in Cal27 but not in HN12, which suggests cancer heterogeneity in this response and a more general impact on CCNE1." (PMID 38954773, 2024). "Studies have shown that higher CCNE1 expression can lead to enhanced metastatic potential, making it a marker for aggressive cancer phenotypes." (PMID 39591374, 2024). "INX-315 is currently being clinically investigated to determine its safety and efficacy in both CCNE1-amplified cancers as well as in CDK4/6i-resistant breast cancer (NCT05735080)." (PMID 38047585, 2024). "Characterized by relative chemoresistance, genomic instability, and poor prognosis, CCNE1-amplified cancers represent an area of unmet need in oncology." (PMID 38047585, 2024). "CCNE1 has been implicated in epithelial-mesenchymal transition (EMT), further promoting cancer cell dissemination." (PMID 39591374, 2024). "In these cancers, CCNE1 amplification is associated with high levels of cyclin E1 protein, CDK2-dependent proliferation, chemotherapy resistance, and a poor prognosis." (PMID 38047585, 2024). "The elevated expression of CCNE1 in various cancers indicates its significant role in tumorigenesis and cancer progression." (PMID 39591374, 2024). "More cell-based studies and clinical experiments are needed to confirm our findings and to further explore interactions between relevant molecules, the precise mechanisms involved, and the potential clinical applications of CCNE1 in cancer." (PMID 39591374, 2024). "A subset of these cancers are driven by CCNE1 amplification and PI3K/AKT alterations that contribute to cell cycle dysregulation and thus these pathways represent promising targets for novel therapeutic approaches." (PMID 38894867, 2024). "CCNE1 amplification is one of the main markers both for synthetic lethality in cancer models and for use of drugs affecting RS in the clinic." (PMID 38279263, 2024).
cancer (continued). "Cyclin-dependent kinase 2 (CDK2) is thought to play an important role in driving proliferation of certain cancers, including those harboring CCNE1 amplification and breast cancers that have acquired resistance to CDK4/6 inhibitors (CDK4/6i)." (PMID 38047585, 2024). "Our preclinical studies demonstrate activity for INX-315 in both CCNE1-amplified cancers and CDK4/6i–resistant breast cancer." (PMID 38047585, 2024). "Given its importance, CCNE1 was selected as the focus of this study to better understand its function in cancer biology." (PMID 39591374, 2024). "We also describe the effects of INX-315 in preclinical models of CCNE1-amplified cancer and use the compound to dissect out the roles of CDK2 and CDK4/6 in treatment-naïve and therapy-resistant luminal breast cancers." (PMID 38047585, 2024). "The frequency of replication fork collapse in CCNE1 overexpressing human fibroblast cells reveals unique fragile sites in the genome, many of which are instability hot spots in cancer and are prone to rearrangement." (PMID 37519629, 2023). "Factors leading to Pt resistance are various, including angiogenesis, hypoxia, immune infiltration, and abnormal regulation of breast cancer susceptibility gene (BRCA), ATP binding cassette subfamily B member 1 (ABCB1) and cyclin E1 (CCNE1), etc.." (PMID 36959862, 2023). "The gastric cancer cell line MKN-7 also exhibits amplification of Cyclin E1 with other cancer lines exhibiting higher protein levels of Cyclin E1." (PMID 36769170, 2023). "The pan-cancer datasets were used to search for links between CCNE1 expression and prognosis, DNA methylation, m6A level, genetic alterations, CCNE1-related genes, and tumor immunity." (PMID 36964635, 2023). "RP6306 demonstrated biased cytotoxicity to CCNE1 amplification cancer cells, whereas adavosertib was both cytotoxic irrespective of CCNE1 background." (PMID 37679326, 2023). "Using the UALCAN online portal, methylation levels at the CCNE1 promoter region were investigated across cancers." (PMID 36964635, 2023). "To examine the correlation between TIICs and CCNE1 expression across cancers, we analyzed the correlation between CCNE1 and the composition of TIICs in various tumors." (PMID 36964635, 2023). "Among these are enhancers for JUP, MYBL2, and CCNE1, and we show that their activity is required for cancer cell viability." (PMID 36803948, 2023). "There were significant correlations between CCNE1 mRNA and several TIICs across cancers, including UCEC." (PMID 36964635, 2023). "A variety of online tools and cancer databases, including GEPIA2, SangerBox, LinkedOmics and cBioPortal, were applied to investigate the expression of CCNE1 across cancers." (PMID 36964635, 2023). "Cyclin E1 deletion emerged as the leading candidate suppressing cell proliferation in Rb-knockout cancer cells, corroborating that CDK2 activation drives cell-cycle entry in the absence of CDK4/6 activity." (PMID 38030655, 2023). "dysregulation of CCNE1/2 activity is present in various cancers, leading to disruption of the G1-S transition and uncontrolled cell proliferation." (PMID 36316768, 2022). "Numerous previous studies have reported that CCNE1, also called cyclin E or cyclin E1, is upregulated in several human cancers and functions as a well-known oncogene." (PMID 35428764, 2022). "Beyond P27, SKP2 also regulates Cyclin E1, an established oncoprotein whose overexpression leads to cell cycle defects that promote cancer development and progression." (PMID 36496990, 2022). "In CRC, the MCF2LAS1/miR-874-3p/FOXM1 axis and MCF2LAS1/miR-874-3p/CCNE1 axis can promote cancer cell apoptosis, inhibit cancer cell proliferation, invasion, migration and EMT process." (PMID 35465322, 2022).